SOX10 (SRY-box transcription factor 10)
Diseases named in the same sentence as SOX10 in open-access papers (continued):
Sharing a sentence is not in itself a finding about the gene and the disease.
tumor (continued). "However, these tumors exhibit diffuse SOX10 and S100 protein expression, whereas our tumor was negative for SOX10." (PMID 40640075, 2025). "Unlike typical solid tumors, immunofluorescence staining for the NC marker Sox10 and the genetic tracer tdTomato showed that most cells were non-recombined stromal cells, while the tdTomato+ tumor cell fraction, just under 40% of all cells, consistently expressed Sox10 (>90%)." (PMID 41063628, 2025). "In the IHC study, tumor cells showed positivity for CD99, EMA, vimentin, and TLE1, while they were negative for NKX2.2, WT1, BCOR, PDGFA, cytokeratins, muscle markers (smooth muscle actin, desmin, caldesmon, MyoD1, and myogenin), and melanocytic markers (HMB45, SOX10, and S100)." (PMID 38339014, 2024). "In addition, 98% of tumors (49 of 50) demonstrated a lack of staining for SOX10, with the remaining tumor demonstrating focal positivity for SOX10 in less than 10% of cells; and 94% (47 of 50) demonstrated no or only focal staining for K5." (PMID 37306115, 2024). "Moreover, analyses of SOX10– and SOX10+MITF– tumors developed in NSG mice at molecular level suggested a profound difference between the tumor types and reflected the tumor growth difference and sustained increased expression of NGFR, JUN, and WNT5A in the SOX10+MITF– melanoma tumors." (PMID 36040798, 2022). "This study aimed to optimize and evaluate automated, IHC-supervised annotation of tumor-cell and normal-cell nuclei in primary and metastatic cutaneous melanoma based on digital H&E/SOX10 dual stains of the same tissue section, but without H&E washout prior to IHC." (PMID 36361209, 2022). "Moreover, SOX6 and SOX10 had a low expression in HCC, which also indicated high grade of tumor." (PMID 35465267, 2022). "Focal staining with CD34 was observed, whereas the tumor was negative for S100 and SOX10." (PMID 32860002, 2021). "Furthermore, independent of initial SOX10 levels, all secondary lesions recapitulated SOX10 expression patterns of the primary tumours, which was high in white matter and low in grey matter regions and bulk." (PMID 33846316, 2021). "Our findings are of clinical relevance as we show that exploiting the aberrant GBM injury-like response through niche-independent upregulation of SOX10, locked tumour cells in the differentiated, non-proliferative state and suppressed tumourigenesis in preclinical models of the disease." (PMID 33846316, 2021). "Tumor cells are positive for S100, SOX10, and CD34 and negative for MUC4." (PMID 33526082, 2021). "In addition, SOX10, a transcription factor of the sex determining region Y (SRY)-related high motility group (HMG)-box gene family, playing an important role in cancer progression, including tumorigenesis, changes in the tumor microenvironment, and metastasis." (PMID 33941222, 2021). "Strikingly, SOX10 expression was restricted to Schwann cells and absent from tumor cells." (PMID 32595833, 2020). "In sum, mechanisms of drug resistance are numerous and distinct subpopulation of resistant cells with either high SOX10 and high MITF expression or low SOX10 and low MITF expression may exist in the same tumor, rendering difficult to completely eliminate the tumor with one targeted treatment." (PMID 31118886, 2019). "Dual immunohistochemical staining of CD3 and CD8 with the melanoma marker SOX10 demonstrated brisk infiltration with CD3+ and CD8+ T cells in both surgically resected in transit metastases, suggesting a T cell mediated immune response against the tumor in both samples." (PMID 28716097, 2017). "However, ectopic expression of SOX10 in SW620 cells led to cobblestone morphology in monolayer cultures, with tight cell-cell contacts characteristics of normal epithelial cells, indicating that SOX10 most likely reversed tumor cell EMT." (PMID 25301735, 2014).
tumor (continued). "Furthermore, the tumor in our case also did not harbor alterations commonly reported in intracranial schwannomas, such as ARID1A/B, DDR1, or SOX10 mutations, suggesting that it might arise from a different mechanism than intracranial schwannomas." (PMID 40255822, 2025). "ERBB2‐amplified ILBC had higher tumor stage (p < 0.0001), more frequent positive nodal status (p = 0.00022), more distant metastases (p = 0.012), and higher histological grade (p < 0.0001), and were more often hormone receptor negative (p < 0.001) and more often SOX10 positive (p = 0.005)." (PMID 38335502, 2024). "In addition, through differential expression analysis on the cell types that predominantly occupy the tumor and muscle regions based on the deconvolution of eMCI, some key genes with spatial heterogeneity of spatial expression patterns were detected, such as PAICS, MITFA, SOX10, and COX6A2." (PMID 39494219, 2024). "However, negative for myogenic markers including desmin and myogenin, can readily exclude the possibility of embryonic RMS, and absence of expression of S100 protein and SOX10 together with retained expression of H3K27me3 disagree with a malignant triton tumor." (PMID 35125107, 2022). "The explanation for the lack of SOX10, in the context of the remainder of the staining profile of this case, could either be that during tumourigenesis, the tumour lost SOX10 expression or that the lack of SOX10 staining was a consequence of freezing during tissue transport." (PMID 35323240, 2022). "In addition, SOX10 has been shown to affect cell fate decisions in neural lineage development in mice, and was described to antagonise the function of the transcription factor NFIA in driving astrocytic differentiation in normal development and later, overexpression in mouse tumour models." (PMID 33339831, 2020). "Likewise, the embryonic origin of neuroblastic tumor cells can be established using NCSC protein markers such as Phox2b and c-kit while embryonic glial-lineage markers such as SRY box 10 transcription factor (Sox10) and AP2α are expressed in immature glial cells in NBT." (PMID 19216736, 2009). "The tumor was positive for CD99, SATB2, TLE1, cyclin D1, and focal FLI1, while negative for EMA, S100, desmin, calponin, and SOX10." (PMID 41869091, 2026). "The tumor cells exhibited positivity for CK7 (partial), CK20, CDX2, and CAM5.2, while being negative for GCDFP15, S100, SOX10, GATA3, PAX8, and CK5/6." (PMID 40438862, 2025). "Immunohistochemically, vimentin, smooth muscle actin (SMA), and P16 were diffuse positive in tumor cells, whereas desmin, cytokeratin (CK), P40, P63, CK5, HMB45, MyoD1, myogenin, S100, and SOX10 were all negative." (PMID 39872225, 2025). "Diffuse membrane–cytoplasmic expression of CK7 was noted in 100% of tumor cells; the reaction with CK20, p63, and SOX10 was negative." (PMID 41375883, 2025). "Other scholars have discovered that Sox10 knockout effects on tumor growth on CD8+ T cells, which is a negative correlation with SOX10 and immune-related pathways." (PMID 40342816, 2025). "Immunohistochemically, vimentin, SMA, and P16 were diffuse positive in tumor cells, whereas desmin, CK, P40, P63, CK5, HMB45, MyoD1, myogenin, S100, and SOX10 were all negative." (PMID 39872225, 2025). "The immunophenotype of the tumor did not reveal a clear line of origin, with negative staining for GFAP, OLIG2, S100 protein, SOX10, desmin, pankeratin, synaptophysin, and only focally positive vimentin." (PMID 40159593, 2025). "Immunohistological examination showed that the tumor cells were positive for EMA and negative for cytokeratin AE1/AE3, p63, desmin, CD34, S100, GFAP, and SOX10." (PMID 40766037, 2025).
tumor (continued). "The tumor was negative for cytokeratin AE1/AE3, p63, desmin, CD34, S100, glial fibrillary acidic protein (GFAP), and SOX10." (PMID 40766037, 2025). "Immunohistochemically, the tumor cells were positive for CD34 and negative for smooth muscle actin, desmin, SOX10, S100, EMA, MUC4, and STAT6." (PMID 40677885, 2025). "The recurrent tumour and lymph nodes metastases were completely negative for Melan-A and PRAME, and focally positive for SOX10." (PMID 39001214, 2024). "Using immunohistochemistry, tumor cells diffusely expressed GFAP and showed no or only focal expression of Olig2 and SOX10." (PMID 38581034, 2024). "Immunohistochemical staining revealed that the tumor cells were positive for S-100, HMG-45, Melan-A, and SOX10 and negative for AE1/AE3." (PMID 38289480, 2024). "The tumour cells were completely negative for MelanA and PRAME while showing only focal SOX10 positivity." (PMID 39001214, 2024). "Primary tumor cells were diffusely positive for CK7, CK20, Cam5.2 and negative for SOX10, TTF1, PSA, and CDX2." (PMID 38831459, 2024). "Immunohistochemical analysis revealed that the tumour cells completely lacked expression of MelanA and PRAME, and focally expressed SOX10." (PMID 39001214, 2024). "Among other immunostains not shown, ATRX nuclear expression was retained in all tumor cells, and none of the tumor cells were positive for IDH1 R132H mutant protein, napsin, NKX3.1, CD45, synaptophysin, INSM1, SOX10 protein, p40, CDX2 protein, PSAP, or PSA." (PMID 38845695, 2024). "Using immunohistochemistry, all tumors except one (case #14 which presented a GFAP staining in a part of the tumor) expressed GFAP diffusely, and presented no or only focal immunopositivity for Olig2 and SOX10." (PMID 38581034, 2024). "The tumor was negative for pancytokeratin, CK5/6, p63, MART-1/MelanA, S100, Sox10, p40, CD34, and CD23." (PMID 38247725, 2023). "In the present case, IHC examination of the tumor revealed that vimentin was positively stained, P63, KRT14, S-100 was focally positive, Ki-67(80%), while KRT5/6, KRT7, GFAP, calponin, SMA, KRT-PAN, SOX10, mammaglobin was negative." (PMID 37705036, 2023). "The tumor was negative for HMB45 and MelanA but was positive for S100, SOX10, WT1, CD99, and, focally, smooth muscle actin." (PMID 37373134, 2023). "The tumor cells were negative for AE1/3, Cam5.2, CKIT, DOG1, CD99, SOX10, S100, HMB45, MelanA, Syn, CgA, Trypsin, Desmin, SMA, Caldesmon, collagen type 4, Laminin, Inhibin, Calretinin, STAT6, CD34, ERG, WT1, ER, PR, and SALL4." (PMID 36928336, 2023). "Immunohistochemically, tumor cells were positive for CK, EMA, Vimentin, CD117, CK7, Mammaglobin, S100 and SOX10, but negative for DOG1, CD56, Cga, Syn, CK20, Calponin, SMA, NapsinA and TTF1." (PMID 37803309, 2023). "Tumor cells in the epithelial and mesenchymal regions DOG-1, CD34, S-100, SOX-10, STAT 6, SMA, desmin, Syn, and CgA were negative; SDHB-positive expression; Ki-67 proliferation index was 3%." (PMID 37658451, 2023). "Immunohistochemically, the tumor cells were positive for desmin, MYOD1 and SMA, focally positive for myogenin, while negative for h-caldesmon, SOX10 and S100P." (PMID 35642345, 2023). "The tumor cells did not express pan-cytokeratin, desmin, MyoD1, Myogenin, Melan-A, HMB45, EMA, S-100, SOX-10, IgG4, and pan-TRK." (PMID 37735390, 2023). "Tumor cells in the epithelial and mesenchymal regions were negative for DOG-1, CD34, S-100, SOX-10, STAT 6, SMA, C-Kit, Calretinin, Syn, CgA, TTF-1, ER, and PR." (PMID 37658451, 2023). "Immunohistochemical(IHC) showed that the tumor cells to be positive for vimentin, focally positive for S-100, negative for calponin, SMA, SOX10." (PMID 37705036, 2023).
tumor (continued). "Microscopic examination revealed that the tumor was spindle cell sarcoma, which was diffusely expressed of CD34, vimentin, S-100, and Pan-TRK, but negative for SOX10, EMA, SSTR2, PR, and STAT6." (PMID 35572973, 2022). "Immunohistochemical features of liver aspiration biopsy tissue are as follows: CK19, CK7, CKp, and MUC5AC were positive in tumor cells, while Hepatocyte, CDX-2, TTF-1, HMB45, Melan-A, S100, and SOX10 were negative." (PMID 36686734, 2022). "Preparations isolated from the CC had a strong increase in the proportion of cells positive for SOX10, the majority of which also expressed O4, but not MBP, confirming that transcriptomic signatures reflect changes in tumour cell fate." (PMID 33846316, 2021). "This was confirmed by immunostaining illustrating SOX10 and EGFL8 co-expression by repair SCs in injured nerve tissue and stromal SCs in GNs, while EGFL8 was absent on tumor cells in GN and NB primary tumors." (PMID 33712610, 2021). "IHC studies show the tumor cells to be positive for FLI-1 and negative for S100 protein, SOX10, desmin, myogenin, WT1, SMA, CD34 and pan-cytokeratin." (PMID 34745213, 2021). "The tumor cells were negative for any other melanocytic markers such as S100, Melan A, MITF, SOX10, all myogenic markers (SMA, MSA, desmin, caldesmon) and cytokeratins." (PMID 31309284, 2020). "Immunohistochemically, the tumor cells lacked of reactivity with CD34; CK5/6, EMA, SOX10, S100, desmin, SMA, MDM2 and GFAP." (PMID 32164724, 2020). "Immunohistochemical analysis showed that the tumor was positive for vimentin, S-100, SOX-10 (SRY -Box 10) and negative for smooth muscle actin (SMA), desmin, cytokeratin (CK), CD34, and the ki-67 index was about 3%." (PMID 31860964, 2019). "In our case, the tumor cells were positive for CK7, S-100, SOX10 and negative for PAX-8 and CD10, arguing against a metastatic clear cell RCC." (PMID 29041930, 2017). "Immunohistochemistry for cytokeratin, LCA, S-100, Sox10, Melan A, smooth muscle actin, h-Caldesmon, MDM2, CDK4, p16 and Myo D1 was negative for all tumor cells." (PMID 26208724, 2015). "Repeat immunohistochemical staining revealed tumor cells positive for CD34 and p16, and negative for smooth muscle actin, desmin, S100, and SOX10, except for the lipoblasts, which were positive for S100 and SOX10." (PMID 40677885, 2025). "The tumor cells were also negative for HER2, CK20, SOX10, and p63." (PMID 41143220, 2025). "The tumor is not reactive to pancytokeratin, CD31, STAT6, S100, or SOX10." (PMID 41246587, 2025). "The tumor cells co-expressed CKAE1/3, EMA, and S100, while SOX10, GFAP, p63, and SMA were negative." (PMID 39636306, 2025). "The tumor was difficult to diagnose, exhibiting GFAP and SOX10 negative and MAP2 positive." (PMID 41331048, 2025). "Immunohistochemical analysis confirmed the positive expression of pankeratin, PAX8 and RCC in the tumour cells while showing negative results for SOX10, HMB45 and Melan A. A notably elevated proliferative index, as indicated by Ki‐67 labelling, was observed within the tumour." (PMID 39355743, 2024). "Immunohistochemical analysis revealed the following results: Tumor cells were negative for Ckp, positive for desmin and actin, negative for myogenin, positive for MyoD1, and negative for CgA, S-100, Syn, h-caldesmon, SMA, Sox-10, Pax-8, and GATA3." (PMID 39139286, 2024). "Most notably, the tumor was found to be negative for Brachyury, CD68, SRY-box transcription factor 10 (SOX10), HMB45, glial fibrillary acidic protein, oligodendrocyte transcription factor 2, anaplastic lymphoma kinase, desmin, CD117, synaptophysin, and neurofilament." (PMID 37598295, 2023). "The tumor cells were EMA, LCA, actin, CD34, CKAE1/AE3, S-100, NSE, and SOX-10 negative." (PMID 37469410, 2023).
tumor (continued). "Furthermore, IHC analysis revealed that the Ki-67 labeling index (LI) was 30–40%, indicating highly proliferative tumor cells, and a large portion of tumor cells strongly expressed Pan-TRK, S-100, and CD34, while negative for vimentin, SOX10, and desmin." (PMID 35572973, 2022). "The tumor showed the expression of cytokeratins, such as CK8-18 and AE1/AE3, and typical CD99 expression, whereas immunostaining for thyroglobulin, TTF1, PAX8, calcitonin, CK20, SOX10, ERG, SMA, and NUT was negative." (PMID 36129618, 2022). "A wide range of immunohistochemical stainings were performed, such as CD68, SMA, desmin, EMA, mucin 4, SOX10, S100 and CD34, from which we could not deduce a specific differentiation line of the tumor cells." (PMID 35645621, 2022). "Using tumor-derived cell lines from MMTV-Neu mice lacking SLK and biochemical approaches, we have characterized the signaling mechanisms and relevant DNA elements driving Sox10 expression." (PMID 33985544, 2021). "However, it is highly unlikely that these neoplasms represent undifferentiated OMMs based on the absence of expression of both TYR and SOX10 RNA as well as the lack of immunolabeling for MDX and SOX-10." (PMID 34422947, 2021). "TRPA1 positivity was also observed in a subset of cases negative with pS100, SOX10 and/or SLUG/SNAIL, and these divergent phenotypes may reflect a process of tumor plasticity and dedifferentiation of neural-derived SSs." (PMID 33076385, 2020). "In summary, we report 2 cases of a high-grade tumor diagnosed as non-ITAC of the sinonasal region, characterized by overt hypercellularity, largely solid growth pattern with comedo-like necrosis, immunohistochemical positivity for p40/p63, S100, SOX10, and GATA3, with a recurrent ETV6::NTRK3 fusion." (PMID 37415052, 2023). "(Immunohistochemical stains showed that the tumor cells were positive for desmin and TFE3, while negative for pancytokeratin, CAM5.2, EMA, chromogranin, synaptophysin, NSE, CD45, SMA, HHF35, myogenin, CD117, DOG1, MUC4, S100, SOX10, HMB45, Melan-A, CD31, ERG, TLE1, STAT6, and Cathepsin-K)." (PMID 35001360, 2022). "However, the absence of any other melanotic marker especially SOX-10 and MITF, the absence of a relevant mitotic activity, and the prominent eosinophilic to clear cytoplasm of the tumor cells are clues to look for other tumor types." (PMID 31309284, 2020). "However, TRPA1 also resulted in being expressed in a subset of cases negative with pS100, SOX10 and/or SNAIL and SLUG, and we may speculate that these divergent phenotypes could reflect a process of tumor plasticity and dedifferentiation of neural-derived SSs." (PMID 33076385, 2020).